EZH2 (enhancer of zeste 2 polycomb repressive complex 2 subunit)
Diseases named in the same sentence as EZH2 in open-access papers (continued):
Sharing a sentence is not in itself a finding about the gene and the disease.
pancreatic cancer (continued). "The lncRNA TUG1/enhancer of zeste homolog 2 (EZH2) axis promoted the proliferation, migration, and EMT phenotype of pancreatic cancer cells by sponging miR-382." (PMID 34039257, 2021). "By recruiting EZH2, lncRNA UCA1 regulates the methylation of SOCS3 protein, reduces the expression of SOCS3, and promotes the Gem resistance of pancreatic cancer." (PMID 34868904, 2021). "The results of qRT-PCR showed higher expression of lncRNA UCA1 and EZH2 and lower SOCS3 expression in pancreatic cancer tissues than that in adjacent normal tissues." (PMID 34868904, 2021). "Our previous study found that EZH2 and HDAC3 were negatively correlated with the prognoses of pancreatic cancer patients." (PMID 33299646, 2020). "Another recent study has reported that CDK5-mediated T261-EZH2 phosphorylation facilitates FBW7-mediated EZH2 ubiquitination and proteasome degradation in pancreatic cancer cells." (PMID 33308321, 2020). "In pancreatic cancer, upregulated lncRNA TUG1 binds to and recruits EZH2 to the promoter regions of RND3 and MT2A." (PMID 33050646, 2020). "EZH2 is considered a master regulator of EMT through orchestrating the regulation of the H3K27me3 epigenetic mark, and in pancreatic cancer it has been shown to regulate EMT through miRNA 139-5p." (PMID 35582229, 2020). "LncRNA-TUG1/EZH2 axis was characterized to promote EMT phenotype, cell proliferation and migration in pancreatic cancer through sponging miR-38222." (PMID 31534128, 2019). "Another histone lysine methyltransferase known as the enhancer of zeste homolog 2 (EZH2), also plays an important role in pancreatic cancer progression." (PMID 31238554, 2019). "The expression of EZH2 protein is negatively correlated with FBW7 protein levels in a cohort of human pancreatic cancer specimens, and FBW7 suppresses EZH2 activity and inhibits tumor migration and invasion via degradation of EZH2 in pancreatic cancer cells." (PMID 29556394, 2018). "In an orthotopic pancreatic tumor model, CDF also inhibited the expression of EZH2, NOTCH-1, CD44, EpCAM, and NANOG." (PMID 28611316, 2017). "However, the role of EZH2 in pancreatic cancer and its interaction with MALAT-1 remain unclear." (PMID 26848980, 2016). "In conclusion, our data indicate that EZH2 recruitment by MALAT-1 and subsequent involvement of the complex in the repression of E-cadherin, promotes pancreatic cancer migration and invasion." (PMID 26848980, 2016). "We also investigated the expression levels of the pancreatic cancer stem cell markers ABCG2 and EZH2 by qRT-PCR, and we found that ABCG2 and EZH2 mRNA expression levels were significantly decreased following siRNA-mediated knockdown of PIM-1 expression." (PMID 27596051, 2016). "Previous studies have reported that EZH2 downregulates RUNX3 by inducing histone H3 methylation in various human cancers such as gastric, bile duct, and pancreatic cancers." (PMID 26871294, 2016). "In this study, there was a positive correlation of EZH2 and MALAT-1 expression in pancreatic cancer tissues." (PMID 26848980, 2016). "We have used the tumor tissues from control and CDF-treated animals and here we show that CDF treatment led to decreased expression of Ki-67, EZH2, HIF-1α, VEGF, and EpCAM in pancreatic tumor remnants as assessed by immunohistochemistry." (PMID 23272057, 2012). "Likewise, the progression of pancreatic cancer was influenced by ANLN through the miR-218-5p/LASP1 signaling pathway, which is mediated by EZH2." (PMID 41513610, 2026). "Interestingly, our results showed HIF1α and GLI-1 expressions were also regulated by EZH2, which is consistent to the previous reports that the similar regulatory role of EZH2 in HIF1α and GLI-1 expressions has been shown in lung and pancreatic cancer cells." (PMID 38664825, 2024). "Additionally, the RNA immunoprecipitation (RIP) assay results revealed that SNHG15 inhibited the expression of P15 and KLF2 through EZH2-mediated H3K27ME3, and promoted the proliferation of pancreatic cancer cells." (PMID 38526609, 2024).
pancreatic cancer (continued). "EZH2 may achieve this through its interaction with the lncRNA MALAT-1, which promotes the proliferation and metastasis of pancreatic cancer." (PMID 36902253, 2023). "EZH2 is mainly expressed in the nuclei of pancreatic tumor cells, but not in normal pancreatic cells." (PMID 37198697, 2023). "Accordingly, we found a significantly reduced tumor incidence of KEC- compared to KC mice (42 vs. 81%) and pancreatic tumors that did form in the absence of Ezh2 showed a reduced relative tumor weight." (PMID 35884510, 2022). "Herein, we show that HAT1 knockdown in pancreatic cancer cells increases gemcitabine sensitivity and decreases PVT1/EZH2 complex levels, suggesting that HAT1 may represent a promising therapeutic target in pancreatic cancer." (PMID 34564701, 2021). "Recent studies have found that HOXA-AS2 could directly interact with enhancers of EZH2 and lysine-specific demethylase 1 (LSD1) involved in pancreatic cancer and acute myeloid leukemia." (PMID 34511122, 2021). "Furthermore, the inhibitor of EZH2, TPH1, or 5-HT7 effectively regressed pancreatic tumor growth in a xenografted mouse tumor model." (PMID 34771469, 2021). "Under hypoxic conditions, exosomes secreted by hypoxia-induced PSCs deliver lncRNA UCA1 into pancreatic cancer cells, where lncRNA UCA1 recruits EZH2 and regulates histone methylation level in SOCS3 gene region, thereby augmenting pancreatic cancer resistance to Gem." (PMID 34868904, 2021). "In addition, Pearson’s correlation analysis showed that SOCS3 expression was negatively correlated with the expression of EZH2 (r = -0.75, p < 0.01) and lncRNA UCA1 (r = -0.73, p < 0.01) in pancreatic cancer tissues." (PMID 34868904, 2021). "We also found that the protein but not the mRNA levels of EZH2 were decreased after HAT1 silencing in pancreatic cancer cells." (PMID 34564701, 2021). "HOTAIR could also couple with EZH2 to silence tumor suppressor miR-34a in pancreatic cancer cells, thereby inducing cancer cell proliferation, suggesting the regulatory role of HOTAIR in EZH2/EMT pathway." (PMID 34439315, 2021). "Co-immunoprecipitation assays revealed an interaction between HAT1 and EZH2 in pancreatic cancer cell lines, regardless of endogenous or exogenous expression." (PMID 34564701, 2021). "MALAT-1 could also exert its oncogenic effects through mediation of EZH2, miR-216a, miR-217, miR-200c, or Hippo-YAP signaling in pancreatic cancers." (PMID 34439315, 2021). "Additionally, miR-139-5p transcription is inhibited by EZH2 through upregulating H3K27me3; thereby, the downregulation of EZH2 and the upregulation of miR-139-5p impede EMT in lymph node metastasis pancreatic cancer." (PMID 33014831, 2020). "For example, the EZH2/miR-139-5p axis impeded EMT and LNM in pancreatic cancer." (PMID 32754277, 2020). "It has been found that in pancreatic cancers, HOTAIR-mediated gene repression is both PRC2-dependent and independent; however, in glioma cells, HOTAIR regulates cell cycle progression predominantly via the PRC2 axis (EZH2-dependent)." (PMID 30866496, 2019). "In pancreatic cancer cells (PC) and colorectal cancer tissue (CRC), HOXA cluster antisense RNA2 lncRNA (HOXA-AS2) is involved in cell growth forming a complex with LSD1 and EZH2." (PMID 30866496, 2019). "DUXAP8 induced increase in pancreatic cancer cell proliferation and tumorigenesis may be partly mediated via epigenetically silencing CDKN1A and KLF2 transcription by binding with EZH2 and LSD1." (PMID 30367681, 2018). "However, the tumor suppressive roles of EZH2 were also identified that suppression of EZH2 promotes cancer progression in some cancer types, such as T-ALL, pancreatic cancer and clear cell renal carcinoma." (PMID 29556394, 2018). "In studies with pancreatic cancer cells, hypoxia and HIF have been shown to be important in the expression of IL-6, miR-21, miR-210 and VEGF as well as the CSC-related factors: NANOG, OCT-4 and EZH2." (PMID 28611316, 2017).
pancreatic cancer (continued). "Knockdown of PIM-1 expression in pancreatic cancer cells suppressed proliferation, induced cell cycle arrest, enhanced apoptosis, resensitized cells to gemcitabine and erlotinib treatment, and inhibited ABCG2 and EZH2 mRNA expression." (PMID 27596051, 2016). "In addition, we found a positive correlation between EZH2 and MALAT-1 expression in pancreatic cancer tissues." (PMID 26848980, 2016). "We initially examined EZH2 expression in pancreatic cancer tissues and corresponding adjacent non-cancerous tissues, and confirmed strong EZH2 expression in tumor tissues." (PMID 26848980, 2016). "In addition, EZH2 selective inhibitors EPZ-6438 and DZNeP increased E-cadherin expression in pancreatic cancer cell lines." (PMID 26848980, 2016). "We found that PIM-1 knockdown in pancreatic cancer cells suppressed proliferation, induced cell cycle arrest, enhanced apoptosis, resensitized cells to gemcitabine and erlotinib treatment, and inhibited ABCG2 and EZH2 mRNA expression." (PMID 27596051, 2016). "miR-26a partially influences human pancreatic cancer through the regulation of cyclin E2 and EZH2, but not through cyclin D2." (PMID 24116110, 2013). "Therefore, the present study set out to elucidate the roles of lncRNA UCA1 loaded in PSC-derived exosomes in Gem resistance of pancreatic cancer under hypoxia, and to identify the downstream mechanisms involving histone methylation in SOCS3 gene region and EZH2 recruitment." (PMID 34868904, 2021). "Therefore, ANLN may promote pancreatic cancer cell progression and miR-218-5p/LASP1 signaling axis by mediating EZH2." (PMID 31395079, 2019). "In addition, EZH2/miR-218-5p/LASP1 signaling axis might be involved in ANLN-mediated cell proliferation, colony formation, migration and invasion in pancreatic cancer." (PMID 31395079, 2019). "We previously found that HOTTIP promotes CRC cell proliferation partly via down-regualtion of p21 expression, while IRAIN could promote pancreatic cancer cell growth by binding to histone demethylase lysine-specific demethylase 1 (LSD1) and enhancer of zeste homolog 2 (EZH2)." (PMID 28938648, 2017). "Our earlier studies have shown that CDF could function as a potent anti-tumor agent against human pancreatic tumor in vitro and in vivo by regulating miRNAs, CSC phenotype and function, and multiple cellular signaling pathways such as NF-κB, Akt, COX-2, Notch-1, and EZH2." (PMID 23272057, 2012). "Moreover, EZH2 depletion did not result in a re-expression of p27 in colon cancer cell lines in vitro, at time points where it resulted in highly increased p27 expression in pancreatic cancer cell lines." (PMID 21765901, 2011). "While the same treatment is not sufficient to reduce the size of pancreatic tumors, strategies that potentiated SASP production, such as the use of EZH2 inhibitors, increased the infiltration of NK and T cells and resulted in a more complete antitumoral response." (PMID 39813356, 2025). "However, the relationship between EZH2/miR-218 axis and ANLN in pancreatic cancer progression has not been studied before." (PMID 31395079, 2019).
follicular lymphoma (134 papers, 2011 to 2026). Follicular lymphoma is a form of non-Hodgkin lymphoma characterized by a proliferation of B cells whose nodular structure of follicular architecture is preserved. "Tazemetostat is the first EZH2 inhibitor approved by the FDA; however, its indications are for patients aged 16 years and older with epithelioid sarcoma or relapsed/refractory EZH2-mutated follicular lymphoma." (PMID 40862786, 2025). "A study investigating the prognostic significance of EZH2 mutations in follicular lymphoma found that patients with mutated EZH2 had significantly shorter progression-free survival compared to those with wild-type EZH2." (PMID 40075894, 2025). "In 2020, the FDA approved the EZH2 inhibitor tazemetostat as a first-in-class drug for the treatment of advanced epithelioid sarcoma or relapsed/refractory EZH2-mutated follicular lymphoma." (PMID 40284428, 2025). "There is current FDA approval for TAZ in epithelioid sarcoma, which exhibits PRC2 hyperactivation resulting from SWI/SNF complex mutations, and follicular lymphoma, characterized by EZH2 gain-of-function mutations." (PMID 41000734, 2025). "Some EZH2 gain-of-function mutations are also inhibited by tazemetostat in follicular lymphomas, including Y646X and A637V." (PMID 40805121, 2025). "EZH2 is a histone methyltransferase that has been implicated in the pathogenesis of follicular lymphoma." (PMID 40075894, 2025). "Tazemetostat is an EZH2 inhibitor approved for epithelioid sarcoma and follicular lymphoma with an EZH2 mutation by the US FDA." (PMID 39941725, 2025). "Recently, EZH2 inhibitors, such as tazemetostat, have been developed for clinical use in relapsed/refractory follicular lymphoma where EZH2 mutations are typically gain-of-function." (PMID 38339323, 2024). "The inhibition of EZH2 with tazemetostat has been studied in a phase 2 clinical trial in patients with relapsed/refractory follicular lymphoma; this study showed an 69% objective response rate in the EZH2-mutated cohort." (PMID 39200232, 2024). "Approximately 25% of follicular lymphomas harbor EZH2 mutations, which are associated with a favorable prognosis." (PMID 38773600, 2024). "Advancements in next-generation sequencing have shed light on frequent mutations in epigenetic regulators in follicular lymphoma, with the EZH2 gene being a notable target." (PMID 38773600, 2024). "Pharmacological EZH2 inhibition was proven to be effective in the treatment of entities with activating EZH2 mutations such as Diffuse Large Cell B-Cell as well as Follicular Lymphoma in phase II clinical trials." (PMID 37297005, 2023). "EZH2 is an important epigenetic regulator of normal germinal center formation in B cells, and approximately 20% of patients with follicular lymphoma have gain-of-function mutations in EZH2." (PMID 37760453, 2023). "EZH2 is a known druggable target, with an FDA-approved EZH2 inhibitor (tazemetostat) for EZH2-wild type and EZH2-mutated follicular lymphoma." (PMID 36900160, 2023). "Early studies have found that EZH2 mutations are associated with Bcl-2 rearrangement in follicular lymphoma." (PMID 37988356, 2023). "Tazemetostat (EPZ-6438) is an EZH2 inhibitor recently approved for relapsed or refractory follicular lymphomas carrying EZH2 gain-of-function mutations." (PMID 37460547, 2023). "EZH2 inhibitor tazemetostat showed encouraging efficacy in patients with R/R EZH2 mutation-positive follicular lymphoma with a manageable safety profile in the overall population." (PMID 37853413, 2023). "These gain of function mutations result in catalytically hyperactive EZH2 in 25–27% of germinal center follicular lymphomas and make them vulnerable to EZH2 inhibition therapy." (PMID 36446780, 2022). "The balance of PcG domains has been directly implicated in oncogenesis of follicular lymphoma patients bearing EZH2 gain-of-function mutations (e.g., Y641/A677)." (PMID 36105358, 2022).
follicular lymphoma (continued). "While EZH2 is mutated at multiple sites in hematopoietic neoplasms, the Y646 amino acid is recurrently and significantly mutated in 7–22% of follicular lymphoma (FL) cases, with up to 40% of the mutations specifically a Y646H alteration." (PMID 33801781, 2021). "The Tyr646Asn mutation in EZH2 is frequently identified in both follicular lymphoma and pediatric-type nodal follicular lymphoma in adult patients." (PMID 33778063, 2021). "The results of this clinical trial led to approval of Tazemetostat for relapsed/refractory follicular lymphoma with EZH2 mutations in June 2020." (PMID 33371192, 2020). "In relapsed/refractory follicular lymphoma harboring activating mutations of EZH2, the clinical responses were much more encouraging, with an overall response rate of 69% and 12% complete responses." (PMID 33371192, 2020). "Several missense mutations in the catalytic SET domain of EZH2 have been identified in about 7–12% of follicular lymphoma cases." (PMID 32906688, 2020). "Inhibition of EZH2 enzymatic activity is currently actively evaluated in clinical trials in diffuse large B cell lymphoma and follicular lymphoma, where mutations in EZH2 affect its enzymatic and canonical function." (PMID 30935402, 2019). "Somatic activating mutations of EZH2 have also been found in diffuse large B-cell lymphoma and follicular lymphoma, whereas inactivating mutations have been reported in myeloid neoplasms, suggesting context-dependent roles of EZH2 in tumorigenesis." (PMID 30190472, 2018). "For example, inactivating mutations of EZH2 have been found in follicular lymphoma and diffuse large B cell lymphoma." (PMID 30101054, 2018). "Mutation of EZH2 residue Y646 was found in 7% of follicular lymphoma cases and 22% of diffuse large cell B-cell lymphomas and was coincident with increased H3K27 trimethylation." (PMID 24367637, 2013). "Interestingly, mutations in the catalytic SET domain of EZH2 have been observed in diffuse large B-cell lymphomas and follicular lymphomas, contributing to oncogenic potential of EZH2." (PMID 39934895, 2025). "Rarely, LOF variants may cluster, as seen in follicular lymphoma-associated mutations in EZH2, which concentrate in the SET domain, disrupting S-adenosyl-L-methionine binding." (PMID 40998763, 2025). "The first selective EZH2 inhibitor (tazemetostat) was developed, which demonstrated antitumor activity in B-cell non-Hodgkin lymphoma cell lines and was approved for EZH2-mutated follicular lymphoma." (PMID 40940718, 2025). "The cobas® EZH2 Mutation Test was used first as an investigational diagnostic device to screen patients for the tazemetostat clinical study to evaluate the treatment of two subtypes of NHL: follicular lymphoma (FL) and diffuse large B-cell lymphoma (DLBCL)." (PMID 38096164, 2023). "EZH2 is mutated in nearly 25% of follicular lymphoma (FL) cases." (PMID 36104682, 2022). "EZH2 inhibitor, Tazemetostat, has been approved for patients with relapsed or refractory follicular lymphoma (R/R FL) with EZH2 mutation and who have received at least 2 prior systemic therapies, and for adult patients with R/R FL who have no satisfactory alternative treatment options." (PMID 33879235, 2021). "For example, the EZH2 inhibitor tazemetostat appears to have a very high activity in EZH2-mutated follicular lymphoma and patients with a tumor carrying this mutation may be preferentially treated with this new agent." (PMID 29677173, 2018). "We detect EZH2 mutations in a significant proportion of BCL2-rearranged follicular lymphomas, BCL2-rearranged diffuse large B cell lymphomas, and high-grade B cell lymphomas with concurrent BCL2 and MYC rearrangements (so-called “double-hit lymphomas”), but not in BL." (PMID 22194861, 2011).